OGA (O-GlcNAcase)
Diseases named in the same sentence as OGA in open-access papers (continued):
Sharing a sentence is not in itself a finding about the gene and the disease.
Insulin resistance (16 papers, 2010 to 2025). Increased resistance towards insulin, that is, diminished effectiveness of insulin in reducing blood glucose levels. "Maintenance of elevated O‐GlcNAc levels with an OGA inhibitor led to persistent endothelial insulin resistance even under NG conditions." (PMID 32508185, 2020). "Pharmacological inhibition of OGA or OGA knockdown in skeletal muscle cells also induced insulin resistance." (PMID 30459708, 2018). "Perturbations of OGA activity in cell culture, loss of OGA-1 activity in C. elegans, and OGT overexpression in mouse liver or fat promotes insulin resistance." (PMID 25505447, 2014). "In mammals, increasing O-GlcNAc levels by reducing O-GlcNAcase (OGA) activity or increasing O-GlcNAc transferase (OGT) activity leads to insulin resistance." (PMID 20952811, 2010). "Earlier studies indicated that elevated levels of O-GlcNAcylation—arising from increased expression of O-GlcNAc transferase (OGT) or inhibition of O-GlcNAcase (OGA)—may contribute to insulin resistance via the hexosamine biosynthetic pathway (HBP)." (PMID 41373704, 2025). "Earlier studies suggested that elevated O-GlcNAcylation levels resulting from increased expression of O-GlcNAc transferase (OGT) or inhibition of O-GlcNAcase (OGA) might contribute to insulin resistance through the hexosamine biosynthetic pathway (HBP)." (PMID 38540730, 2024). "Insulin resistance is induced in primary human adipocytes by either the classical method of chronic hyperinsulinemia and hyperglycemia or by directly elevating O-GlcNAc levels using O-GlcNAcase (OGA) pharmacological inhibitors." (PMID 24948903, 2014). "In addition, we used cells where insulin resistance was induced using a more specific OGA inhibitor, GlcNAcstatin, to confirm the regulation we observed by using the less specific OGA inhibitor, PUGNAc." (PMID 24948903, 2014). "PUGNAc is a very potent inhibitor of OGA, but it also strongly inhibits the human lysosomal enzymes, Hex A and B, which increases the ganglioside levels that could impact insulin resistance." (PMID 21358590, 2011). "One way to aid in discriminating which inhibitor has off-target effects, and establish whether increased O-GlcNAc levels independently induce insulin resistance in cultured cells, would be to use a structurally distinct inhibitor of OGA." (PMID 20851343, 2010). "Therefore, studies in cultured cells and in vivo appear to be in agreement that selective inhibition of OGA does not cause insulin resistance." (PMID 20851344, 2010). "In differentiated 3T3-L1 adipocytes, two different OGA inhibitors have been found to increase O-GlcNAc levels but not alter insulin-stimulated phosphorylation of AKT nor induce insulin resistance either." (PMID 22536363, 2012). "Despite a strong correlation of increased O-GlcNAcylation during insulin resistance/diabetes, some studies indicate that reducing this protein modification (by inhibiting OGT or overexpressing OGA) in vitro is not sufficient to prevent insulin resistance in adipocytes." (PMID 37107691, 2023). "Moreover, a sexual dimorphism was observed upon high-fat feeding, with increased adiposity and insulin resistance in OGA+/- female, while OGA+/- males did not develop obesity and showed improved glucose tolerance compared to OGA+/+ males." (PMID 36058931, 2022). "Contrary to earlier reports, enhanced OGA expression combined with insulin stimulation in 3T3-L1 cells has suggested that a decrease in cellular O-GlcNAc does not prevent the onset of insulin resistance, also corroborated with studies using selective OGA inhibitors." (PMID 25336650, 2014).
breast carcinoma (11 papers, 2012 to 2025). "A study of primary human breast cancer demonstrated a decrease in overall O‐GlcNAc levels along with a significant increase in OGA enzyme activity." (PMID 35347892, 2022). "The low OGA expression in MMTV-PyVT cells was consistent with the Oncomine meta-analysis of breast cancer microarray database." (PMID 31645543, 2019). "Manipulation of OGT and OGA activities in breast cancer cells showed that overexpression of OGT enhanced the migration/invasion of breast cancer cells in vitro and lung metastasis in vivo, but did not affect cell proliferation." (PMID 25426101, 2014). "This suggests that the combined detection of HIF-1α, OGT, and OGA in clinical samples may be useful as potential breast cancer biomarkers." (PMID 25426101, 2014). "To identify proteins regulated by OGT and O-GlcNAc cycling that may contribute to CSC phenotypes, we treated MDA-MB-231 breast cancer cells with an OGA inhibitor Thiamet-G (TMG) to block the removal of the modification and increase the extent of protein O-GlcNAcylation." (PMID 40136647, 2025). "In breast cancer 4T1 cells, E-cadherin protein expression was increased by OGT shRNA, while it was decreased by treatment with the pharmacological OGA inhibitors PUGNAc and NButGT." (PMID 23964270, 2013). "A significant increase in cellular UDP-GlcNAc was found in Nic-treated breast cancer cells, whereas no detectable change in OGT or OGA expression was found, suggesting the potential for an increased the HBP flux." (PMID 31019204, 2019).
Hyperglycemia (10 papers, 2012 to 2022). An increased concentration of glucose in the blood. "Mechanistic studies demonstrated that increased PVAT O-GlcNAcylation following chronic hyperglycemia is linked to inhibition of OGA activity." (PMID 29681862, 2018). "In this context, the development of macrophages specific OGT or OGA knock-out mice should provide important clues on the role of this modification in hyperglycemia-induced inflammation." (PMID 25620956, 2014). "They showed that hyperglycemia reduced both mRNA level and promoter activity of SERCA2a in isolated cardiomyocytes and that the effect of hyperglycemia on SERCA2a was attenuated by overexpression of O-GlcNAcase and mimicked by overexpression of O-GlcNAc-transferase." (PMID 22768157, 2012). "Studies in diabetes mellitus have shown that hyperglycemia directly increases protein O-GlcNAcylation, at least in part, by increasing the glucose flux through HBP, and that OGT/OGA expression may be regulated by chronic hyperglycemia." (PMID 34140929, 2021). "During hyperglycemia with activation of the HBP, OGT and OGA expression may be upregulated to manage the increase in the level of UDP-GlcNAc." (PMID 23734074, 2013). "Placental OGT and OGA expression levels both affect placental development; however, maternal stress seems to be the pivotal regulator of OGT and is more critical for fetal neurodevelopment, rather than hyperglycemia." (PMID 34140929, 2021).
bladder cancer (7 papers, 2013 to 2026). "Knockdown of OGA or inhibition of OGA using Thiamet-G was also reported as blunting autophagic flux within bladder cancer cells and cardiomyocytes." (PMID 37918804, 2023). "Some authors have already proposed the measurement of OGT and OGA mRNA in urine as a diagnosis tool in bladder cancer." (PMID 29861440, 2018). "The authors concluded that measurement of OGT and OGA mRNA in urine might be an interesting parameter for the diagnosis bladder cancers." (PMID 23964270, 2013). "Furthermore, in prostate carcinoma and bladder cancer cells, while the level of OGT/O-GlcNAcylation increased, the level of deglycosylase OGA decreased, prompting a dynamic imbalance between OGT and OGA." (PMID 33194731, 2020). "O-GlcNAcylation levels in bladder cancer cells were altered through pharmacological or genetic manipulations: treating with 6-diazo-5-oxo-norleucine (DON) or thiamet-G (TG) or up- and downregulation of O-GlcNAc transferase (OGT) or O-GlcNAcase (OGA)." (PMID 32174982, 2020).
colon cancer (7 papers, 2014 to 2024). "Increased protein O‐GlcNAc modification and changes in the level of OGT or OGA expression are commonly observed features of many types of cancer, including leukemia, breast, prostate, and colon cancers." (PMID 35347892, 2022). "We next investigated the effects produced by perturbation of O-GlcNAc levels on the expression of stem cell markers CD44 and CD133 by pharmacological inhibition of OGT or OGA in colon cancer cells." (PMID 31139149, 2019). "We then investigated the consequences of OGA downregulation on the entry into TIS of colon cancer cells, hypothesizing that it could potentially delay or prevent the establishment of the senescence phenotype in response to low-dose chemotherapy." (PMID 39426963, 2024). "OGA+/− mice exhibited a higher incidence of colon tumors than OGA+/+ mice." (PMID 25915426, 2015). "In a previous work, we showed that artificially modulating O-GlcNAcylation levels in colon cancer cells, led to compensatory adjustments in OGT and OGA in an attempt to restore basal O-GlcNAcylation levels." (PMID 39426963, 2024). "To determine the levels of O-GlcNAcylation, OGT expression, and OGA expression in colon cancer cells compared to non-malignant colon cells, we performed FACS analysis, Western blot analysis, and immunofluorescence assays." (PMID 31139149, 2019). "On the other hand, OGA protein levels quickly decreased after Cre-mediated knockout of OGT in mouse embryonic fibroblasts, but OGA knockdown in colon cancer cells did not significantly decrease OGT protein expression." (PMID 25520704, 2014).
colorectal cancer (7 papers, 2014 to 2024). A primary or metastatic malignant neoplasm that affects the colon or rectum. "Microarray analysis in the colorectal cancer SW620 metastatic clone revealed that O-GlcNAcase silencing caused O-GlcNAcylation elevation and altered the expression of about 1300 genes." (PMID 29867058, 2018). "The expression of nucleolin is altered during OGA downregulation in colorectal cancer cells, and we have shown previously that O-GlcNAcylation regulates nucleolar processes." (PMID 39395807, 2024). "In two independent microarray data sets, the expression of OGA and OGT was significantly associated with poor cancer-specific survival of colorectal cancer (CRC) patients." (PMID 25000257, 2014). "However, in another separate study, inhibiting OGA in colorectal cancer cells promoted the level of O-GlcNAcation, thus promoting the expression and activity of β-catenin and E-cadherin and further induce EMT phenotype of cancer cells and promote tumor metastasis." (PMID 36275679, 2022). "In this study, we characterized eight colorectal cancer cell lines and one non-cancerous cell line for O-GlcNAc-related profiles such as the expression of OGT, OGA, and total protein O-GlcNAcylation, along with their sensitivity toward OSMI-1 (Os), an OGT inhibitor (OGTi)." (PMID 39413067, 2024).
type 2 diabetes (7 papers, 2011 to 2024). "It appeared that a single nucleotide polymorphism in MGEA5, encoding OGA, is associated with type 2 diabetes in a mexican american population." (PMID 30459708, 2018). "The OGA gene is also implicated with the development of type II diabetes since single nucleotide polymorphism in the MGEA5 gene has been linked to the occurrence of type II diabetes in a Mexican population." (PMID 21358590, 2011). "In the insulin resistance pathway, protein O-GlcNAcase (oga), which was involved in glycoprotein metabolism and can suppress the development of type II diabetes is up-regulated." (PMID 36290180, 2022). "Moreover, Goto-Kakizaki rats, which develop type 2 diabetes mellitus in early life, express an inactive 90 kDa isoform of OGA." (PMID 30459708, 2018). "In leucocytes from patients with type 2 diabetes, the TXNIP mRNA level was significantly correlated with OGA, but not with OGT mRNA." (PMID 35887161, 2022).
colitis (6 papers, 2015 to 2024). Inflammation of the colon. "Consistent with the results of acute colitis, OGA+/−mice showed increased susceptibility to chronic colitis compared with OGA+/+ mice." (PMID 25915426, 2015). "In contrast to our findings, a recent work showed that OGA+/− knockout mice are susceptible to DSS‐induced colitis, suggesting that hyper‐O‐GlcNAcylation may promote intestinal inflammation by activating NF‐κB signaling." (PMID 29941542, 2018). "OGA+/− mice have higher susceptibility to DSS-induced colitis than OGA+/+ mice." (PMID 25915426, 2015). "In this study we used OGA+/− mice with constitutively elevated colonic O-GlcNAc levels as an experimental model to investigate the role of O-GlcNAcylation in intestinal inflammation and colitis-associated cancer." (PMID 25915426, 2015). "Immunohistochemistry staining indicated that OGT level was significantly reduced while OGA was obviously elevated in model group, which confirmed that colitis leads to a reduction in colonic O-GlcNAcylation level." (PMID 34399822, 2021). "To investigate the functional role of O-GlcNAcylation in colitis, we used OGA heterozygote mice, which have an increased level of O-GlcNAcylation." (PMID 25915426, 2015). "Colitis was induced in OGA+/+and OGA+/−mice by administration of 2% DSS in drinking water for 7 days, followed by normal drinking water." (PMID 25915426, 2015). "Severe colitis of OGA+/−mice were reflected by histopathological image analysis with higher histological scores and colonic shortening compared to OGA+/+ mice." (PMID 25915426, 2015). "Our results demonstrated that WMW can enhance OGT activity and suppress OGA activity, thereby increasing RIPK3 O-GlcNAcylation, and then inhibiting necroptosis, eventually alleviating TNBS-induced colitis." (PMID 34399822, 2021). "O-GlcNAcase (OGA) that is enriched in Bacteroides and Firmicutes can hydrolyze O-GlcNAcylated protein in epithelial cells and immune cells, which can inhibit the development of colitis." (PMID 34858414, 2021). "To determine whether pharmacologically elevated protein O‐GlcNAcylation strengthens barrier function and protects mice from chemical‐induced acute colitis, we orally administered water or Thiamet‐G (TMG, an OGA inhibitor) to C57BL/6 mice (n = 5) for 2 weeks." (PMID 29941542, 2018). "Consequently, OGA+/− mice exhibited increased Iκb and STAT3 phosphorylation compared with WT mice during colitis." (PMID 25915426, 2015). "In summary, we demonstrated the role of O-GlcNAcylation in colitis and CAC using OGA+/− mice." (PMID 25915426, 2015). "In this study, we demonstrated that the classic Chinese herbal formula WMW can alleviates TNBS-induced mice colitis, and the mechanisms involved may be as followed: WMW treatment can regulate colonic OGT and OGA activities, that is, enhance OGT activity and suppress OGA activity." (PMID 34399822, 2021).
hepatocellular carcinoma (6 papers, 2015 to 2025). A malignant tumor that arises from hepatocytes. "For instance, APS impeded O-GlcNAc synthesis by decreasing OGT and augmenting OGA levels in doxorubicin (Dox)-treated Hep3B hepatocellular carcinoma (HCC) cell, leading to exacerbated Dox-induced ER stress, as evidenced by elevated CHOP expression." (PMID 41155562, 2025). "In hepatocellular carcinoma (HCC) patients, high O-GlcNAcylation levels and low expression of OGA mRNA are associated with high frequency of HCC recurrence." (PMID 33535386, 2021). "Increased O-GlcNAcylation was also associated with poor survival in cholangiocarcinoma patients, while OGA downregulation predicted recurrence in hepatocellular carcinoma after liver transplantation." (PMID 30123425, 2018). "Importantly, we found that PCK1 inhibits motility of hepatoma cell via downregulating cellular O-GlcNAcylation levels by detecting the cellular motility in response to OGT or OGA inhibition." (PMID 34650217, 2021). "Aberrant hyper-O-GlcNAcylation is reported to yield hepatocellular carcinoma (HCC) malignancy, but the underlying mechanisms of the OGT/OGA imbalance responsible for HCC tumorigenesis remain largely unknown." (PMID 34298689, 2021).
endometrial cancer (5 papers, 2013 to 2023). Primary or metastatic malignant neoplasm involving the endometrium (mucous membrane that lines the endometrial cavity). "Endometrial cancers have a high incidence of mutations in the genes encoding the O-GlcNAc cycling enzymes, O-GlcNAc transferase (OGT) and O-GlcNAcase (OGA)." (PMID 36052252, 2022). "Regarding the endometrial carcinomas, it appeared that OGT and OGA mRNA were significantly more elevated in grades II and III tumors than in grade I. In addition, OGT and OGA expression was higher in case of cancers with deep myometrial invasion." (PMID 23964270, 2013).
glioblastoma (5 papers, 2021 to 2025). The most malignant astrocytic tumor (WHO grade IV). "In order to investigate the mechanisms of OGT/OGA and protein O-GlcNAcylation on gene regulation in cancer, we decided to determine the effect of OGT and OGA knockdown in human glioblastoma cells." (PMID 37689115, 2023). "Here, we have investigated the role of OGT and OGA enzymes in glioblastoma cells through their chemical inhibition and gene knockdown." (PMID 37689115, 2023). "Therefore, in order to understand the role of OGT and OGA in glioblastoma, we depleted the levels of these enzymes in U87 cells by using shRNAs delivered through lentivirus." (PMID 37689115, 2023). "Label-free LC-MS/MS quantitative proteomic analysis of control and iOGA groups (O-GlcNAcylation dynamics disrupted with OGA inhibitor Thiamet G) identified altered Gal-3 expression in glioblastoma (GBM) secretome, predicting Gal-3 could be a substrate for O-GlcNAc addition and removal." (PMID 40723900, 2025). "Interestingly, the O-GlcNAcase inhibitor promoted ACSS2 Ser-267 phosphorylation in glioblastoma cells, without affecting normal astrocytes, highlighting its potential for further application in glioblastoma therapy." (PMID 40097417, 2025). "Gene Expression Profiling Interactive Analysis (GEPIA) showed lower OGA expression in lung adenocarcinoma (LUAD), lung squamous cell carcinoma (LUSC), and glioblastoma multiforme (GBM) compared to standard samples, indicating increased O-GlcNAcylation in tumors." (PMID 39667498, 2024).
lung adenocarcinoma (5 papers, 2017 to 2025). A carcinoma that arises from the lung and is characterized by the presence of malignant glandular epithelial cells. "In a study using CL1–5 human lung adenocarcinoma cells, the reduction in O‐GlcNAcylation caused by treatment with the GFAT inhibitor DON was shown to reduce OGA gene and protein expression levels." (PMID 40937539, 2025). "We have previously revealed a positive correlation between OGT and OGA protein expression in lung adenocarcinoma tissues." (PMID 33801653, 2021). "When cultured CL1-5 or A549 human lung adenocarcinoma cells were treated with an OGA inhibitor, either Thiamet G (TMG) or PUGNAc, to elevate O-GlcNAcylation, the amount of OGT protein decreased while that of OGA increased." (PMID 33801653, 2021). "We used immunohistochemistry to explore the utility of OGT, OGA, and O-GlcNAc as potential biomarkers for lung adenocarcinoma." (PMID 30123425, 2018). "We also observed a positive correlation between OGT and OGA levels in lung adenocarcinoma, and high levels of both enzymes predicted poor patient outcomes." (PMID 30123425, 2018). "We assessed relationships between OGT, OGA, and O-GlcNAc levels in lung adenocarcinoma tissues using the Spearman rank correlation analysis." (PMID 30123425, 2018). "In addition, recent analyses of OGT and OGA expression using the Oncomine cancer microarray database found elevated OGT mRNA in lung adenocarcinoma tissues compared with normal lung tissues in most datasets." (PMID 30123425, 2018). "In this study, the expression of OGT, OGA, and O-GlcNAc were examined in lung adenocarcinoma tissues using immunohistochemistry, and the clinicopathological features as well as patients’ outcome were evaluated to assess the prognostic relevance of these markers." (PMID 30123425, 2018). "Consistently, our findings that only OGT, but not OGA or O-GlcNAc level in tumors independently predicts survival implies that the key lever in tipping O-GlcNAcylation homeostasis of lung adenocarcinoma is OGT expression." (PMID 30123425, 2018).